IL1B (interleukin 1 beta)
Diseases named in the same sentence as IL1B in open-access papers (continued):
Sharing a sentence is not in itself a finding about the gene and the disease.
hyperuricemia (continued). "Ruminococcus positively correlated with TJ proteins (ZO-1), in contrast, negatively correlated with inflammatory cytokines (IL-1β and IL-6), LPS, and UA, indicating Ruminococcus had a positively effect on hyperuricemia." (PMID 33104864, 2021). "The results showed that the expression of the NLRP3 inflammasome in peripheral blood mononuclear cells, and the levels of IL-1β and IL-18 in the plasma were upregulated in the gouty nephropathy group compared with the control and hyperuricemia groups." (PMID 34305953, 2021). "Hyperuricemia induced a state of inflammation and significantly increased IL-1β and TNF-α levels (P < 0.05), while decreasing serum levels of IL-10." (PMID 32528050, 2020). "It was found that IL-1β and IL-18, two inflammatory cytokines, was up-regulated in subtotal nephrectomy or hyperuricemia-induced renal tubular injury." (PMID 30807290, 2019). "As expected, the concentrations of multiple inflammatory cytokines including tumor necrosis factor-alpha (TNF-α), interleukin-1 beta (IL-1β) and interleukin-6 (IL-6) were higher in the kidney of the hyperuricemia group than those in the CON group, indicating the presence of inflammation." (PMID 41009565, 2025). "Additionally, serum levels of inflammatory cytokines (IL-1β, IL-6) were notably elevated, indicating severe kidney tissue reactions and confirming the presence of uric acid nephropathy in hyperuricemia mice." (PMID 38257077, 2024). "A correlation between CR and IL-1β in hyperuricemia has been found." (PMID 39483458, 2024). "The current study indicated that hyperuricemia patients had significantly higher tear IL‐1β levels." (PMID 36988248, 2023). "The molecular mechanism of its specific action may be related to the inhibition of the TLR4/MyD88 signaling pathway and the NLRP3 inflammasome activation, thereby reducing IL-1β production in high fructose-induced hyperuricaemia mice." (PMID 38041694, 2023). "The results indicated that CF and CF60 could significantly down-regulate the levels of sUA, CRE, sXOD, lXOD, and IL-1β in hyperuricemia rats." (PMID 36797795, 2023). "Moreover, it lessens renal concentrations of TNF-α, IL-1β, and IL-6 in mouse models of hyperuricemia, thereby mitigating renal impairment." (PMID 38094893, 2023). "Previous studies have shown that IL-1β could be induced in the cardiac of hyperuricemia rats and promoted cardiac damage." (PMID 36986461, 2023). "Activation of TLR4 and the NLRP3 inflammasome promotes the maturation and release of caspase-1, along with downstream cytokines such as IL-1β and IL-18, triggering a persistent pro-inflammatory state crucial for the continued progression of hyperuricaemia nephropathy." (PMID 38041694, 2023). "Subsequently, it promoted the expressions of inflammation factors IL-1β and TNF-α, causing immune dysfunction and leaky gut syndrome, followed by exaggerated immune response and intestinal barrier dysfunction, which triggered hyperuricemia progression." (PMID 36432519, 2022). "Hyperuricemia can promote the expression of inflammatory cytokines, such as IL-1β, TNF-α, and IL-6." (PMID 34444825, 2021). "In addition, the tlr6 knockdown rats suffering from hyperuricemia showed the lower level of IL‐1β and an ameliorative cardiac function." (PMID 32558367, 2020). "Clearly there are other, as yet unknown, factors that determine whether production of IL-1β occurs as a result of hyperuricemia." (PMID 30761138, 2019). "As IL-1β plays a pivotal role in the development of pain and inflammation in the context of hyperuricemia or MSU accumulation in the joint, it can be suggested that the analgesic and anti-inflammatory effects of P. pinnata extracts are related to their IL-1β inhibition capacity." (PMID 31885654, 2019). "This study highlighted that chronic hyperuricemia may influence inflammatory responses by facilitating IL-1β production in peripheral blood leukocytes." (PMID 29326934, 2017).
hyperuricemia (continued). "Moreover, there were positive associations between tear uric acid level and tear IL‐1β level in total participants and the hyperuricemia group, but not in the control group." (PMID 36988248, 2023). "Therefore, uric acid-triggered IL-1β-dependent inflammation might be a key link between hyperuricaemia and its co-morbidities." (PMID 33748660, 2021). "Therefore, in case of ABCG2 dysfunction, the subjects have hyperuricemia first by renal urate overload and intestinal urate under-excretion; and then increased release of IL-1β (by macrophages) and IL-8 (by ECs) invoke further neutrophilic recruitment and gouty flare." (PMID 29453348, 2018). "Hyperuricemia triggers systemic inflammation through ROS-mediated NF-κB activation and peroxidase inhibition, elevating TNF-α, IL-6, and IL-1β." (PMID 40870677, 2025). "Consistent with previous research, we also observed that hyperuricemia resulted in increased production of proinflammatory and profibrogenic factors, such as TGF-β1 and IL-1β." (PMID 38436813, 2024). "A similar study observed that L. plantarum Q7downregulated the levels of IL-1β, TNF-α, and MDA in hepatic and nephritic homogenate, indicating improved antioxidant activity and relief inflammation symptoms in the treatment of hyperuricemia mice." (PMID 38674582, 2024). "The polyphenols extracted from purple potato leaves inhibited the levels of IL-1β, IL-6, and TNF-α, as well as serum creatinine, and also decreased the levels of expression of XOD in the liver of hyperuricemia mice, thus protecting the kidney." (PMID 38674582, 2024). "The geniposide-phospholipid complex reduces levels of inflammatory cytokines (TNF-α, IL-6, and IL-1β) in hyperuricemic mice and regulates the PI3K/AKT/NF-κB signaling cascade to improve post-hyperuricemia chronic kidney disease." (PMID 38094893, 2023). "In these analyses, the plasma IL-1β concentrations and the PBMC caspase-1 and ASC gene and protein expression were significantly higher in UAN compared to hyperuricemia patients." (PMID 35204131, 2022). "The protein expression of NLRP3, ASC, and Caspase-1 in the kidney tissue of hyperuricemia mice and the level of mice inflammatory cytokines NLRP3 and IL-1β was significantly reduced; this change was demonstrated at each dose in the dosing groups." (PMID 36120294, 2022). "Berberrubine has been shown to significantly reduce serum urate levels and the levels of inflammatory mediators (IL-1β, IL-6, and TNF-α) in mice with PO- and hypoxanthine-induced hyperuricemia." (PMID 36483739, 2022). "The production of IL-1β, IL-6 and ICAM-1 was also decreased in the WPP-treated group and CPP-treated group to inhibit the inflammatory process in hyperuricaemia." (PMID 35087407, 2021). "In a hyperuricemia animal model, uric acid can upregulate the expression of inflammatory factors such as cyclooxygenase-2 (COX-2), IL-1β, and TNF-α and play an important role in the development of complications related to hyperuricemia." (PMID 33897800, 2021). "The ICAM-1, IL-1β and IL-6 levels were measured to evaluate the anti-inflammatory effects of WPP and CPP on the treatment of hyperuricaemia." (PMID 35087407, 2021). "Another interesting aspect of uric acid and hyperuricaemia is the role of urate as an activator of the NLRP3 inflammasome, and thereby of IL-1β production." (PMID 33748660, 2021). "The pro-inflammatory role of hyperuricemia provides the rationale for targeting NLRP3 and IL-1β as a potential disease-modifying therapy for neurological disorders." (PMID 24511458, 2013). "Hyperuricemia amplifies these processes: xanthine oxidase-derived reactive oxygen species, reduced nitric-oxide bioavailability, and, to a larger extent, NLRP3 inflammasome activation (IL-1β/IL-18) allow for near-constant “inflammatory priming”." (PMID 41515581, 2025). "However, chronic hyperuricemia can activate NLRP3 inflammasome, promote macrophage infiltration and IL-1β release in adipose tissue, and induce adipocyte hypertrophy and fibrosis." (PMID 40376050, 2025).
hyperuricemia (continued). "Hyperuricemia triggers several inflammatory signaling pathways, with the TLR4/NF-κB axis being especially important in promoting the release of pro-inflammatory cytokines such as IL-1β, MCP-1, and TNF-α." (PMID 40963680, 2025). "One animal study on mice with hyperuricemia found that CGA could protect against elevated levels of UA, BUN, Cr, and reduce inflammation through the inhibition of LPS, IL-1β, and TNF-α among other inflammatory factors and related signaling pathways." (PMID 40821993, 2025). "In the preceding results, it was observed that EST could effectively reduce the expression levels of inflammatory cytokines PGE2, IL-1β, and TNF-α in PO-induced hyperuricemia mice." (PMID 38540830, 2024). "Innate immune pathways are also increasingly considered to play an important role in the pathogenesis of hyperuricemia, and particularly lead to activation of the NLRP3 inflammasome which contributes to the release of IL-1β and other pro-inflammatory cytokines." (PMID 34819865, 2021). "In this study, we evaluated the therapeutic potential of WPP and CPP in the treatment of hyperuricaemia by measuring XO activity inhibition, the levels of UA, Cr and UN in serum and urine and the expression of ICAM-1, IL-1β and IL-6, and by observing kidney histological damage." (PMID 35087407, 2021). "Furthermore, bergenin decreased the serum levels of IL-6, IL-1β, and TNF-α in hyperuricemia mice, and promoted a polarization shift from the M1 to M2 phenotype in RAW264.7 cells." (PMID 32850823, 2020). "In comparison to the CON group, the mRNA levels of inflammatory and stress markers, including IL-1β, TNF-α, and IL-6, were approximately twofold higher (p < 0.001) in the hyperuricemia group, indicating a significant upregulation of these genes in response to hyperuricemia (HUA)." (PMID 41009565, 2025). "Notably, Shiwei-Ruxiang powder has been observed to ameliorate renal impairment by diminishing CRE and BUN levels, while also counteracting the concentrations of pro-inflammatory agents like TNF-α and IL-1β, along with the expression of phospho-p38 MAPK, within hyperuricemia mice." (PMID 38094893, 2023). "Importantly, no significant alterations in serum LPS, IL-1β, TNF-α, or intestinal permeability were observed before the onset of hyperuricemia (on the 3rd), confirming the association between hyperuricemia and systemic inflammation." (PMID 38088975, 2023). "Our data suggest that leukocytes of patients respond to the presence of hyperuricemia and comorbidities, expressing ABCG2 and IL-1β genes differentially compared to normouricemic and nondisease states." (PMID 35505381, 2022). "SX, CF30 and CF90 could significantly decrease XOD and IL-1β, or CRE levels in hyperuricemia rats but did not affect uric acid." (PMID 36797795, 2023). "It is noteworthy that hyperuricemia may stimulate inflammatory leukocytes through epigenetic modification such as histone methylation, even without MSU crystals, thereby increasing production of IL-1β, IL-6, and TNF-α." (PMID 33568990, 2020).
acute kidney injury (75 papers, 2012 to 2026). Sudden and sustained deterioration of the kidney function characterized by decreased glomerular filtration rate, increased serum creatinine or oliguria. "Knockdown of caspase-4/5 preserved human TECs from cell death and reduced the release of mature IL-1β, and in caspase-11-deficient mice, contrast-induced acute kidney injury was abrogated, indicating a central role for caspase-11 in acute kidney injury." (PMID 30250284, 2018). "In this study, we verified that medium from Hyp-pretreated mASC significantly ameliorated levels of serum creatinine, neutrophil gelatinase-associated lipocalin, and inflammatory cytokines IL-1β and IL-6 in the serum of mice during acute kidney injury." (PMID 29890767, 2018). "Fatal outcome from pulmonary hemorrhages was associated with low TNF-α, high IL-1β, and high iNOS expression, a pattern possibly expressed also in dogs with other forms of acute kidney injury." (PMID 26824356, 2016). "Additionally, proinflammatory cytokines such as TNF-α, IL-6, and IL-1β have been shown to be associated with cisplatin-induced acute renal failure." (PMID 24171038, 2013). "In the present study, we found that SSR significantly reversed the secretion of IL-1β and downregulated the expression of HIF-1α, c-Myc, and IL-1β proteins in residual renal tissue of rats with renal failure, which may be associated with the improvement of renal function and RIF." (PMID 34211565, 2021). "Histological analysis showed kidney lesions, disrupted serum biomarkers (blood urea nitrogen and creatinine) related to acute kidney injury, and elevated pro-inflammatory mediators (IL-1β, IL-6, TNF-α)." (PMID 39217203, 2025). "Many recent studies have reported that betanin supplementation reduces the levels of inflammatory cytokines such as TNF-α, IL-1β and IL-6 in various conditions, from stomach ulcers to testicular toxicity, from acute kidney injury to alcoholic liver disease." (PMID 41515203, 2025). "Previous studies on the pathogenesis of acute renal failure have demonstrated that NF-κB inhibitors can significantly reduce the production of IL-1β and IL-18 in albumin-stimulated HK-2 cells." (PMID 36732854, 2023). "The treatment with SeNPs coated with lycopene markedly halted the rise in the levels of TNF-α, IL-1β, IL-6, and gene expression of nitric oxide synthase in acute kidney injury-mediated renal inflammation." (PMID 37902021, 2023). "This oxidative stress is linked to renal failure and triggers an initial inflammatory response mediated by proinflammatory mediators TNF-alpha and IL-1b, and a transcriptional factor, NF-κB." (PMID 35056564, 2022). "si-PVT1 diminished levels of TNF-α, IL-6 and IL-1β in lipopolysaccharide-induced HK-2 cells, thus alleviating inflammation and acute kidney injury." (PMID 34775377, 2021). "In the acute kidney injury study, inflammatory cytokines such as IL-1β, IL6, and TNF-α were measured in mice 16 h after intraperitoneal injection of LPS." (PMID 34327209, 2021). "AKI is previously known as acute kidney failure, and the study found that repurified LPS can activate the caspase-1/IL-1β pathway during acute kidney failure, leading to pyroptosis." (PMID 34007404, 2021). "The evaluation of different inflammatory mediators such as TNF-α, IL-1β, IL-6 and NF-κB verified the protective effects of linalool (50 and 100 mg/kg) against cisplatin-induced acute kidney injury." (PMID 33126443, 2020). "Inflammatory cytokines such as IL-6, IL-1β and NF-kB also reported contributes in the development of renal failure and level of them was found to ameliorated in Cinnamtannin A2 treated 5/6 nephractomized rats." (PMID 32385622, 2020). "To assess direct tissue injury, we measured kidney mRNA expression of KIM‐1 and NGAL, which are elevated in renal failure, and the inflammatory markers IL‐6, IL‐1β, and TNFα." (PMID 31102342, 2019). "Renal levels of IL-1β, IL-18, and IL-6 and neutrophils have been reported to be higher in cisplatin-induced acute kidney injury." (PMID 30691208, 2019).
acute kidney injury (continued). "In recent years, it has been intensively reported that NLRP3 inflammasome/Caspase-1/IL-1β signaling pathway was involved in renal tubular lesion during acute kidney injury." (PMID 31616439, 2019). "NF-κB is a well-known regulator of the transcription of inflammatory gene including TNF-α, IL-1β, and IL-6 during acute kidney injury." (PMID 28465474, 2017). "Treatment of SNx animals with theracurmin improved structural and functional manifestations of cardiac injury associated with renal failure and also attenuated cardiac NLRP3 inflammasome activation and mature IL-1β release." (PMID 28000751, 2016). "Recently, we reported that transgenic (Tg) mice overexpressing HCaRG/COMMD5 in RPTs recovered rapidly from the inflammatory burst that increased TNF-α and IL-1β as well as infiltration of macrophages after acute kidney injury (AKI)." (PMID 24515317, 2014). "Similarly, in canines, cytokines including IL-1 alpha, IL-1β, and transforming growth factor-β and the enzyme 5-lipoxygenase are increased in acute kidney injury (AKI) and CKD." (PMID 38590952, 2024). "Others have also found that BMP7 treatment led to significant reductions in proinflammatory cytokines, including TNF, in macrophages in vivo and that BMP7 represses TNF and IL1B in models of chronic and acute renal failure and in chondrocytes from patients with osteoarthritis." (PMID 32973129, 2020). "Likewise, it attenuated the increase in the plasma concentrations of pro-inflammatory cytokines including IL-1β and IL-6 induced by renal failure." (PMID 29774097, 2018). "The mRNA abundance of cytokines (IL-1α, IL-1β, IL-8, IL-10, TNF-α, TGF-β) and enzymes (5-LO, iNOS) was measured prospectively in blood leukocytes from 34 dogs with severe leptospirosis and acute kidney injury, including 22 dogs with leptospirosis-associated pulmonary hemorrhages." (PMID 26824356, 2016). "Acute kidney injury is characterized by a high inflammatory state, reduced cytokine clearance, and elevated levels of systemic cytokines, such as interleukin (IL)-17A, IL-6, IL-8, IL-1β, IL-12, and tumor necrosis factor (TNF)-α, which aggravate lung injury and increase the risk of lung infection." (PMID 39724279, 2024). "In the study of acute kidney injury (AKI), as an upstream signal of inflammatory pathways, NF-κB and MAPK were activated by a series of inflammatory responses associated with AKI, leading to the production of large amounts of downstream inflammatory cytokines such as IL-6, TNF-α and IL-1β." (PMID 35744798, 2022). "Quercetin-3-O-glucoside can inhibit the expression of TNF-α, IL-1β and IL-6 and the activation of NF-κB, and simultaneously up-regulate the expression of Nrf-2 and HO-1, and inhibit the inflammation and oxidation to resist the induction of cisplatin of acute kidney injury in mice." (PMID 32748813, 2020). "Moreover, it has been shown that the concentrations of PAF in plasma and urine are significantly increased in patients with acute renal failure during septic shock, accompanying with high levels of the pro-inflammatory cytokines including IL-1β, IL-6, IL-8, and TNF-α." (PMID 29950994, 2018). "In a model of cisplatin-induced acute kidney injury, APF significantly reduced the levels of IL-1β, IL-6, TNF-α and MCP-1 by inhibiting the mincle/Syk/NF-κB signaling pathway." (PMID 37362082, 2023). "The interaction between NPs and cytokines was demonstrated by the administration of ANP to rats with acute kidney injury induced by I/R where it inhibited mRNA expression of TNF-α, IL-1β, and IL-6 in the lung and kidney." (PMID 29774097, 2018). "G. vaginalis-exposed mice displayed higher levels of IL-1α, IL-1β, TNF-α, MIP-1β, and IL-2 in the kidney and higher levels of serum creatinine, a biomarker of acute kidney injury, than PBS controls." (PMID 28358889, 2017). "Acute kidney injury is triggered by the production of harmful free radicals and inflammatory processes, with elevated levels of inflammatory cytokines like TNF-α, IL-6, and IL-1β." (PMID 39093465, 2025).